SOSTDC1 (sclerostin domain containing 1)
Description:
May be involved in the onset of endometrial receptivity for implantation/sensitization for the decidual cell reaction Enhances Wnt signaling and inhibits TGF-beta signaling (By similarity). Directly antagonizes activity of BMP2, BMP4, BMP6 and BMP7 in a dose-dependent manner.
Synonyms: Ectodin; USAG1; CDA019; DKFZp564D206; DAND7
Tractability: Antibody: UniProt places it where antibodies can reach, with high confidence; UniProt predicts a signal peptide or a membrane-spanning region; its Gene Ontology location is reachable by antibodies, with medium confidence.
Gene: Protein-coding gene on chromosome 7 (16,461,481 to 16,530,580, reverse strand). Ensembl gene ENSG00000171243.
Subcellular location: Secreted
Subcellular location (Human Protein Atlas): Golgi apparatus; Nucleoli; Nucleoli rim; Vesicles; Predicted to be secreted
Gene Ontology:
Molecular function: BMP binding; BMP receptor activity
Biological process: negative regulation of BMP signaling pathway; negative regulation of determination of dorsal identity; negative regulation of myoblast differentiation; negative regulation of Wnt signaling pathway; BMP signaling pathway; negative regulation of cell differentiation
Cellular component: extracellular region
Genetic constraint (gnomAD): Loss-of-function variants: 7 observed, 15.88 expected, observed/expected ratio (o/e) 0.44, 90% interval 0.25 to 0.83. The upper end of that interval is the gene's LOEUF score, 0.83, which puts it in group 3 of 6, group 1 being the genes least tolerant of losing a copy. Missense variants: 242 observed, 271.96 expected, observed/expected ratio (o/e) 0.89, 90% interval 0.8 to 0.99. Synonymous variants: 94 observed, 97.59 expected, observed/expected ratio (o/e) 0.96, 90% interval 0.81 to 1.14.
Homologues: Orthologues: chimpanzee SOSTDC1 (100% identical), chimpanzee SOSTDC1 (99% identical), macaque SOSTDC1 (99% identical), dog SOSTDC1 (98% identical), guinea pig SOSTDC1 (98% identical), pig SOSTDC1 (97% identical), mouse Sostdc1 (95% identical), rat Sostdc1 (95% identical), rabbit SOSTDC1 (91% identical), tropical clawed frog sostdc1 (73% identical), zebrafish sostdc1a (61% identical), zebrafish sostdc1b (59% identical). Paralogues in human: SOST (38% identical).
Diseases named in the same sentence as SOSTDC1 in open-access papers:
SOSTDC1 is named in the same sentence as 59 diseases in open-access papers, as found by Europe PMC text mining. Sharing a sentence is not in itself a finding about the gene and the disease. The quoted sentences say what the papers report.
breast carcinoma (11 papers, 2015 to 2024). "Because SOSTDC1 is closely associated with luminal breast cancer, we divided the samples into hypo- and hypermethylation groups based on SOSTDC1 methylation levels." (PMID 29642861, 2018). "SOSTDC1 mRNA levels are downregulated in breast cancer and are associated with survival." (PMID 29642861, 2018). "We found both mRNA expression and protein expression of SOSTDC1 in BRCA1‐wildtype breast cancer cells were lower than that in BRCA1‐mutant ones, which was also confirmed by public dataset analysis." (PMID 38864559, 2024). "Sostdc1 was also frequently downregulated in primary breast cancers (98.2%), and Sostdc1 promoter hypermethylation at CpG sites inhibited cell proliferation and survival, while E4BP4 reduced Sostdc1 expression and its promoter activity in breast cancer cells." (PMID 36338475, 2022). "Sostdc1 blocks the Smad phosphorylation induced by BMP7 without diminishing BMP2 or Wnt3a-induced signalling in breast cancer cells, indicating that Sostdc1 is a clinically important extracellular regulator of various signalling pathways in breast cancer." (PMID 36338475, 2022). "Extracted data on SOSTDC1 methylation for breast cancer and the control samples indicated that SOSTDC1 methylation levels were significantly higher in cancer tissues than in control tissues (P = 3.05E-36)." (PMID 29642861, 2018). "In breast cancer cells, SOSTDC1 modestly increases Wnt3a signalling, decreases BMP-7 signalling, whilst eliciting little effect on BMP-2-induced signalling." (PMID 28733469, 2017). "SOSTDC1 also plays a vital role in the development of various cancers, such as breast cancer, renal tumors, Wilms tumor and gastric cancer." (PMID 26378658, 2015). "As the synthetic‐lethal interaction of PTEN and CHD1 is present in breast cancer, whether the regulation of SOSTDC1 on CHD1 affected by PTEN status?" (PMID 38864559, 2024). "In addition, the regulation of breast cancer by Sostdc1 is correlated with its methylation, as the methylation levels of Sostdc1 were evidently lower in control tissues than in cancer tissues." (PMID 36338475, 2022). "The elevation in SOSTDC1 methylation level in tumour tissues may explain SOSTDC1 downregulation in breast cancer because promoter methylation has an inhibitory effect on gene expression." (PMID 29642861, 2018). "As a transcriptional modulator, E4BP4 can inhibit the activity of FOXO142 and is also involved in SOSTDC1 downregulation in breast cancer cells;23 its mechanisms of action are currently unknown." (PMID 30250199, 2018). "Future studies might focus on the combination of SAM40 and SOSTDC1 in the prognostic prediction of luminal breast cancer." (PMID 29642861, 2018). "In breast cancer, methylation also participated in the down-regulation of SOSTDC1." (PMID 26378658, 2015). "Moreover, E4BP4, a transcriptional repressor, could bind to the promoter of SOSTDC1 gene and induce CpG hyper-methylation, thereby leading to repressed SOSTDC1 expression in breast cancer." (PMID 27087917, 2016). "Hence, combination of SOSTDC1, DACT2 and WIF1 was effective in differentiating breast cancer [non-invasive and invasive] from benign diseases of the breast and healthy individuals and could help as a complementary diagnostic tool for breast cancer." (PMID 34997107, 2022). "In thyroid cancer, breast cancer, and non-small cell lung carcinoma (NSCLC), SOSTDC1 being able to restrict proliferation is under-expressed." (PMID 35333898, 2022). "SOSTDC1, a secreted regulator of both BMP and Wnt signalling pathways, is under expressed in breast cancer and can differentially affect signalling induced by Wnt3a, BMP-2 and BMP-7." (PMID 28733469, 2017). "Four marker genes (ID4, SOSTDC1, SLC26A2, TNC) relevant to drug activity to cisplatin on breast cancer cells were derived from the signature genes for breast cancers." (PMID 26824188, 2016).
breast carcinoma (continued). "Moreover, multivariate diagnostic analysis of the methylation status of WIF1, Sostdc1, and DACT2 showed up to 91% specificity and 100% sensitivity in discriminating breast cancer (invasive and non-invasive) from benign tumours and controls and may be a complementary tool for breast cancer diagnosis." (PMID 36338475, 2022).
thyroid cancer (11 papers, 2015 to 2023). "As a modulator of cell proliferation and differentiation, Sostdc1 is associated with the development and progression of multiple cancer types, including breast, renal, gastric, and thyroid cancers." (PMID 36338475, 2022). "To understand specific mechanisms underlying the inhibitory effect of SOSTDC1 on thyroid cancer cell proliferation, we examined the protein expression level of cell cycle regulators by Western blot analysis." (PMID 26378658, 2015). "In addition, Sostdc1 expression was downregulated in thyroid cancer, which was associated with the hypermethylation of its promoter." (PMID 36338475, 2022). "Our results underline a fundamental role of SOSTDC1 as a tumor suppressor in thyroid cancer." (PMID 26378658, 2015). "A previous study demonstrated that Sostdc1 inhibits hepcidin secretion and suppresses the proliferation of thyroid cancer cells." (PMID 36338475, 2022). "Recently, Sostdc1 has been found to be closely related to the development and progression of multiple cancer types, including breast, renal, gastric, and thyroid cancers." (PMID 36338475, 2022). "Sostdc1 is involved in the progression and development of multiple cancer types, including breast, gastric, renal, bladder, and thyroid cancers." (PMID 36338475, 2022). "For instance, Cyclin A2 and Cyclin E2 can be mediated by SOSTDC1 and potentiate cell proliferation in thyroid cancer." (PMID 32154226, 2020). "E2F signature was significantly enriched in low SOSTDC1 expression group, in comparison with high expression group, indicating preferential E2F activation in thyroid cancer specimens with low SOSTDC1 expression." (PMID 26378658, 2015). "Similar with the previous studies, our data demonstrated that decreased cyclin A2 and cyclin E2 were involved in the anti-proliferative role of SOSTDC1 in thyroid cancer." (PMID 26378658, 2015). "To further validate the expression of SOSTDC1 in thyroid cancer, we used real-time polymerase chain reaction (PCR) to determine the expression levels of SOSTDC1 in 22 pairs of tumors and their adjacent non-tumorous thyroid tissues." (PMID 26378658, 2015). "In our present study, for the first time SOSTDC1 was found to be down-regulated and functioned as a tumor suppressor gene through inhibiting cell proliferation in thyroid cancer." (PMID 26378658, 2015). "We also further explored the potential mechanism by which SOSTDC1 suppresses thyroid cancer cell proliferation." (PMID 26378658, 2015). "The results showed that over-expression of SOSTDC1 in thyroid cancer cells resulted in dys-regulating the expression of critical cell cycle regulators, cyclin A2 and cyclin E2 in vitro and vivo." (PMID 26378658, 2015). "In conclusion, our data demonstrate that SOSTDC1 is down-regulated in thyroid tumor tissues and inhibits thyroid cancer cell proliferation through modulating cyclin A2 and cyclin E2." (PMID 26378658, 2015). "Ectopic over-expression of SOSTDC1 inhibited proliferation and induced G1/S arrest in thyroid cancer cells." (PMID 26378658, 2015). "To further evaluate the role of SOSTDC1 in thyroid cancer progression, we analyzed the correlation between SOSTDC1 expression and clinical features of patients." (PMID 26378658, 2015). "To further investigate the functional influences and the involved pathways of down-regulated SOSTDC1 on thyroid cancer, we downloaded RNAseqV2 data sets for 358 cases of thyroid cancers from the TCGA data portal." (PMID 26378658, 2015). "To investigate the functional role of SOSTDC1 in thyroid cancer progression, we established two stably expressed SOSTDC1 thyroid cancer cell lines, K1/SOSTDC1 and 8505C/SOSTDC1." (PMID 26378658, 2015). "In addition, a recent cell study found a new pathway of E4BP4/G9a/SOSTDC1/hepcidin linking cellular iron dysfunction to thyroid cancer." (PMID 32092884, 2020). "SOSTDC1 inhibits cell proliferation and differentiation and induces G1/S arrest in thyroid cancer." (PMID 28938548, 2017).
thyroid cancer (continued). "Together, our results demonstrate that SOSTDC1 is down-regulated in thyroid cancer and might be a potential therapeutic target in the treatment of thyroid cancer." (PMID 26378658, 2015). "In this study, we show that SOSTDC1 is down-regulated in thyroid cancer." (PMID 26378658, 2015). "Therefore, SOSTDC1 inhibits the growth of thyroid cancer cells in vivo, likely by decreasing cyclin A2 and cyclin E2." (PMID 26378658, 2015). "Moreover, ectopic over-expression of SOSTDC1 led to down-regulation of cyclin A2 and cyclin E2, which subsequently inhibit thyroid cancer cell proliferation in vitro and in vivo." (PMID 26378658, 2015). "To evaluate the clinical relevance of SOSTDC1 in thyroid cancer, we investigated the SOSTDC1 protein expression in 16 cases of goiters, 15 cases of adenomas, and 107 cases of thyroid cancers (26 cases FTC, 69 cases PTC, and 12 cases ATC) by immunohistochemistry." (PMID 26378658, 2015). "We demonstrated that SOSTDC1 was significantly down-regulated in thyroid cancer." (PMID 26378658, 2015). "The current study demonstrated that SOSTDC1 expression was significantly reduced in thyroid cancer." (PMID 26378658, 2015). "Moreover, our data suggest that SOSTDC1 inhibits the proliferation of thyroid cancer cells via regulation of cyclin A2 and cyclin E2." (PMID 26378658, 2015). "Taken together, these data suggested that SOSTDC1 is down-regulated in thyroid cancer and the altered expression of SOSTDC1 may play an important role in the process of cancer progression." (PMID 26378658, 2015). "As it is well known that E2F widely participates in the development of various cancers, we focused on studying whether E2F is involved in the effect of SOSTDC1 on the thyroid cancer cells." (PMID 26378658, 2015). "Interestingly, low expression of SOSTDC1 was detected in 88.8% thyroid cancer (95/107), whereas SOSTDC1 is highly expressed in most goiter (13/16) and adenoma specimens (12/15)." (PMID 26378658, 2015). "Collectively, these data indicate that SOSTDC1 inhibits proliferation of thyroid cancer cells." (PMID 26378658, 2015). "SOSTDC1, a BMP4/7 antagonist also regulates hepcidin synthesis, providing a new path for cellular iron deficiency in the thyroid gland through the E4BP4/G9a/SOSTDC1/hepcidin pathway, which can be reduced hepcidin secretion and thyroid cancer cell proliferation." (PMID 36895478, 2023). "Moreover, down-regulation of SOSTDC1 was also observed in thyroid cancer." (PMID 27087917, 2016). "However, the mechanisms involved in down-regulation of SOSTDC1 in thyroid cancer are largely unknown." (PMID 26378658, 2015). "Thus, it is likely that epigenetic mechanisms might also play a role in down-regulation of SOSTDC1 in thyroid cancer." (PMID 26378658, 2015). "However, the expression pattern and biological significance of SOSTDC1 in thyroid cancer are largely unknown." (PMID 26378658, 2015). "This was the case for SEMA5A (FDR = 0.0855), DRD2 (FDR = 0.00623) and SOSTDC1 (FDR = 0.0234), which have all been found to act as tumor suppressors in pancreas cancer, glioma, non-small cell lung cancer and thyroid cancer." (PMID 34604945, 2021). "Mechanistically, SOSTDC1 silencing by E4BP4 and G9a complex-mediated promoter hypermethylation promoted hepcidin secretion in thyroid cancer." (PMID 33868231, 2021). "However, the expression and biologic function of SOSTDC1 in thyroid cancer remains unclear." (PMID 26378658, 2015). "The results showed that SOSTDC1 expression was attenuated in thyroid cancer tissues compared to adjacent non-tumorous thyroid tissues." (PMID 26378658, 2015).
gastric cancer (8 papers, 2015 to 2024). A primary or metastatic malignant neoplasm involving the stomach. "In gastric cancer, SOSTDC1 acts like a tumor suppressor, and its silencing can promote tumor growth and lung metastasis." (PMID 36778919, 2023). "SOSTDC1 plays a tumor-suppressive role in gastric cancer cells, as SOSTDC1 knockdown accelerates tumor growth and metastasis." (PMID 35864961, 2022). "Further research is required to provide a comprehensive understanding of the role of Sostdc1 as a prognostic marker in gastric cancer as well as its tumour suppressor properties." (PMID 36338475, 2022). "Circ _0001190 served as an miR-586 sponge, regulating Sostdc1 expression, and miR-586 promoted gastric cancer advancement by interfering with Sostdc1." (PMID 36338475, 2022). "The expression of SOSTDC1 is down-regulated in gastric cancer, and ectopic over-expression of SOSTDC1 in gastric cancer cells suppressed cell proliferation, cell cycle progression and anchorage-independent growth." (PMID 27087917, 2016). "Recently, it was demonstrated that SOSTDC1 protein expression was down-regulated in gastric tumors, and ectopic over-expression in gastric cancer cells inhibits their tumorigenic properties." (PMID 26378658, 2015). "In addition, exosomal circ_0001190 overexpression suppressed cell vitality, migration, proliferation, and invasion of gastric cancer through the miR-586/Sostdc1 axis." (PMID 36338475, 2022). "Sclerostin, encoded by the sclerostin domain-containing protein 1 (SOSTDC1) gene, was recently found to be negatively correlated with the aggressiveness of non-small cell lung cancer and gastric cancer as lower expression was observed in metastases compared to primary tumors." (PMID 32486027, 2020). "Furthermore, Sostdc1 showed tumour suppressor properties in gastric cancer, and its silencing enhanced the movement of cancer cells, accelerated tumour growth, and promoted the formation of lung metastases by inhibiting the SMAD and c-Jun N signalling pathways." (PMID 36338475, 2022). "Furthermore, the raised expression level of SOSTDC1 can inhibit tumor growth in gastric cancer." (PMID 35333898, 2022). "Conversely, by acting as a miR-587 sponge to adjust the expression of the sclerostin domain-containing 1 (SOSTDC1), circ-0001190 overexpression inhibited cell viability, proliferation, angiogenesis, migration, and invasion of gastric cancer cell lines." (PMID 38392967, 2024). "In addition to BMP4 overexpression of in diffuse-type gastric cancer cells, BMP signalling was modulated by secreted-type antagonists such as Sostdc1, CER1, CKTSF1B1, Noggin, and Chordin." (PMID 36338475, 2022).
non-small cell lung carcinoma (6 papers, 2016 to 2022). A group of at least three distinct histological types of lung cancer, including non-small cell squamous cell carcinoma, adenocarcinoma, and large cell carcinoma. "SOSTDC1 regulates the expressions of p21Cip and p27Kip to inhibit the proliferation of non-small-cell lung cancer cells." (PMID 28938548, 2017).
clear cell renal carcinoma (4 papers, 2010 to 2022). A malignant epithelial neoplasm of the kidney characterized by the presence of lipid-containing clear cells within a vascular network. "Specifically, a 7p21 homozygous deletion has been identified in 9 of 97 Wilms tumor, resulting in loss of SOSTDC1, and loss of heterozygosity at 7p has also been reported to cause SOSTDC1 reduction in clear cell renal cell carcinoma." (PMID 27087917, 2016). "For example, it has been reported that SOSTDC1 is significantly down-regulated in clear cell renal carcinoma and over-expression of SOSTDC1 inhibits proliferation of clear cell carcinoma cells through regulating both BMP and Wnt signaling." (PMID 26378658, 2015). "Consistent with a potential role for SOSTDC1 as a tumor suppressor, SOSTDC1 expression was statistically significantly decreased in both adult clear cell renal carcinoma and pediatric Wilms tumors." (PMID 21080955, 2010). "Additionally, Sostdc1 levels were lower in renal clear cell carcinoma, and Sostdc1 suppressed renal carcinoma cell proliferation by inhibiting Wnt3a signalling and the phosphorylation of R-Smads-1, -5, and -8 induced by BMP7." (PMID 36338475, 2022). "The restoration of Sostdc1 signalling may suggest a novel strategy for treating renal clear cell carcinoma." (PMID 36338475, 2022). "For example, it was previously indicated that SOSTDC1 is significantly down-regulated in clear cell renal carcinoma and over-expression of SOSTDC1 inhibits its proliferation through suppressing BMP-7-induced phosphorylation of Smad-1, -5, and -8, as well as Wnt-3a signaling." (PMID 26378658, 2015). "There is a significant reduction in SOSTDC1 in Wilms tumors and renal clear cell carcinoma." (PMID 21080955, 2010).
colorectal cancer (4 papers, 2015 to 2023). A primary or metastatic malignant neoplasm that affects the colon or rectum. "Research has demonstrated that SOSTDC1 plays a role in promoting invasion of colorectal cancer and liver metastasis by interacting with ALCAM/CD16635." (PMID 38012244, 2023). "Bartolomé and colleagues have recently reported that ALCAM, via its interaction with SOSTDC1 (sclerostin domain containing-1), increases the hepatic metastases from colorectal cancer." (PMID 34680335, 2021).